FOXP3 (forkhead box P3)
Diseases named in the same sentence as FOXP3 in open-access papers (continued):
Sharing a sentence is not in itself a finding about the gene and the disease.
Autoimmunity (continued). "An age-independent but relatively lower FOXP3 expression for Treg cell development was associated with autoimmune disorders despite a reversed Th17/Treg ratio in contrast to that in the patients without PIDs." (PMID 32670274, 2020). "IPEX syndrome is also caused by mutations in the FOXP3 gene and is characterized by defective Tregs, multisystem inflammation, and autoimmunity, with death usually by 2 years of age unless successfully treated." (PMID 30741720, 2019). "The non-redundant role of Tregs in establishing immune homeostasis is exemplified by the development of multi-organ autoimmunity in humans and mice that harbor mutations in the Foxp3 locus." (PMID 31776355, 2019). "Treg cells were initially described as a CD4+CD25high T cell population whose depletion is associated with the development of severe multi-organ autoimmunity, and were defined by the expression of the transcription factor forkhead box P3 (FoxP3)." (PMID 31956323, 2019). "In humans, the strongest evidence linking Treg dysfunction and autoimmunity comes from patients with the immunodysregulation polyendocrinopathy enteropathy X-linked (IPEX) syndrome that have loss-of-function mutations in the FOXP3 gene." (PMID 30723474, 2019). "Mice deficient in Foxp3+ T cells develop fatal autoimmune disease, and continuous expression of Foxp3 throughout life prevents autoimmunity." (PMID 29725328, 2018). "The lack of IL-2, its high affinity receptor chain IL-2Rα/CD25 or its transducing chain IL-2Rβ/CD12220, lead to the development of wasting autoimmunity as a result of the loss of stable Foxp3 expression and subsequent Foxp3+ Treg cells in the periphery." (PMID 30560927, 2018). "By contrast, FOXP3+ Treg cells are essential for mediating immune tolerance, and deficiency of Treg cells is often linked with autoimmunity." (PMID 30150979, 2018). "Humans that carry mutations in the transcription factor forkhead box P3 (FOXP3) or have depletion in Tregs develop severe autoimmunity." (PMID 30483058, 2018). "Tregs are vitally important in the maintenance of self-tolerance and prevention of autoimmunity, and the X-linked master regulator transcription factor FoxP3 drives their generation, maintenance, and function." (PMID 30337927, 2018). "Our results were expected for flow cytometry analysis, in addition we performed histone marks analysis at the FOXP3 genomic regulatory regions, partially overlapped with CNS regions associated with autoimmunity." (PMID 30671056, 2018). "The increase in IL6 signaling observed in T1D patients modulates immune response through the expansion of pathogenic Th17 cells and inhibition of generation of Foxp3 + T-regulatory cells is associated with T1D autoimmunity." (PMID 29445381, 2018). "In accordance with this, the absence of GATA-3, transcription factor associated with Th2 cells in Tregs, led to autoimmunity, defective FOXP3 expression, and elevated cytokine levels specific of Th1, Th2, and Th17 cells." (PMID 28589115, 2017). "In both CTLA4-deficient and Foxp3-deficient mice, autoimmunity is driven by CD4 effector pathology, and depletion of Tregs in adult mice is associated with rapid onset of autoimmune pathology." (PMID 28646041, 2017). "With the ultimate goal of controlling the devastating autoimmunity resulting from mutations of FOXP3 in IPEX syndrome, we envisaged the possibility of performing adoptive transfer of functional autologous Tregs generated in vitro." (PMID 29075264, 2017). "Our work has shown that absence of OX40 and CD30 costimulatory signals prevents CD4 T cell–driven autoimmunity in Foxp3-deficient mice, suggesting a novel way to block these side effects." (PMID 28646041, 2017). "FoxP3 was identified from early studies with scurfy mice, which have an idiopathic mutation in the Foxp3 gene and develop systemic multi-organ autoimmunity." (PMID 28983300, 2017).
Autoimmunity (continued). "Mutations within the FOXP3 gene or deletion of FOXP3 in transgenic mouse models can result in the development of fatal autoimmunity." (PMID 29391874, 2017). "The deficiency of the CTLA-4 gene produces serious autoimmune disorders similar to those induced by defective FOXP3, demonstrating that CTLA-4 is essential for Treg function." (PMID 28589115, 2017). "Stable expression and activity of Foxp3 is essential to the development and maintenance of functional Treg cells, and Foxp3-mutant Scurfy mice experience lethal autoimmunity, as do humans with Foxp3 mutations, unless treated." (PMID 29236775, 2017). "A large body of experimental work in autoimmunity and transplantation has implicated Foxp3+ Tregs in orchestrating and sustaining dominant mechanisms of tolerance, allowing a constant control of Teff." (PMID 28321218, 2017). "The phenotype of FOXP3 knockouts gives the “scurfy” phenotype in mice and in humans generates the X-linked autoimmunity–allergic dysregulation and immuno-dysregulation, X-linked syndromes." (PMID 26187646, 2015). "Of note, even though most expanded populations of Foxp3+ Treg cells exhibit suppressive activity, tissue-associated or antigen-specific Treg cells appear superior in suppressing local autoimmune disorders such as RA." (PMID 25152867, 2014). "We posit that the aging-associated DNA hypomethylation-driven increase in FoxP3 expression constitutes a strategy for keeping autoimmunity in check as organisms age." (PMID 24325345, 2014). "The NF-kB pathway is also important for nTreg stability, probably contributing to Foxp3 transcription through c-Rel, since TRAF6 deficiency in nTregs promoted the loss of Foxp3 expression and Th2 type autoimmunity." (PMID 25133199, 2014). "Functionally, transfer of these Foxp3-deficient ‘TREG’ cells into lymphopenic hosts led to severe autoimmunity, indicating that these cells acquired pathogenic potential and retained self-antigen specificity." (PMID 23345540, 2013). "On the other hand, it is well known that impaired Treg function is also associated with pathogenesis of autoimmune disease, and that CD4+/CD25+/Foxp3+ cells represent one of the major Treg cells involved in susceptibility/resistance to autoimmunity." (PMID 22028728, 2012). "Our data suggest that point mutations in Foxp3 can have different effects than the widely recognized mutations that lead to the development of autoimmunity in scurfy mice and patients with IPEX syndrome." (PMID 22247766, 2012). "Foxp3-expressing Tregs are a constitutively occurring T cell subpopulation, whose deficiency is associated with development of autoimmunity, and which controls adaptive immune responses both in health and disease." (PMID 22428018, 2012). "Deletion or mutations of Foxp3 cause lethal autoimmunity in scurfy mice and profound morbidity in patients suffering from IPEX (immune dysregulation, polyendocrinopathy, enteropathy, X-linked)." (PMID 22247766, 2012). "Mutations in Foxp3 are responsible for the scurfy (sf) mutant mouse and for the autoimmune human diseases including the X-linked fatal “immune dysregulation, polyendocrinopathy, enteropathy, X-linked” (IPEX), autoimmune colitis, and RA." (PMID 23133752, 2012). "Our observation that IL-12 abrogates Foxp3 expression in T cells during activation further confirms the pro-inflammatory and the potential pathogenic effects of this cytokine in autoimmunity." (PMID 21779356, 2011). "IL-12 is recognized for its ability to promote Th1 type of pathogenic T cell response in many autoimmune conditions and can overcome immune tolerance by suppressing Foxp3+ Tregs." (PMID 21779356, 2011). "FOXP3 is a critical player in Treg cell differentiation and maintenance and deficiency of FOXP3 in both humans and mice is associated with multi-organ autoimmunity and lymphoproliferative disorders." (PMID 18980674, 2008).
Autoimmunity (continued). "In pediatric patients, severe immune dysregulation in IPEX syndrome (Immune dysregulation, polyendocrinopathy, enteropathy, X‐linked syndrome), caused primarily by mutations in the FOXP3 gene located on the X chromosome, leads to defective regulatory T cell function and widespread autoimmunity." (PMID 41476811, 2026). "Finally, all treatments led to a slight increase in the number of Foxp3+CD4+ T cells in tumor, a fact that highlights the inhibitory effect of P60 on Foxp3 activity rather the depleting cells that is associated with the development of autoimmunity." (PMID 39075226, 2025). "Previous work has shown that a constitutive reduction in Foxp3 protein levels of approximately 80% caused by an mRNA-destabilizing reporter gene insertion in the 3’ UTR of the mouse Foxp3 gene was sufficient to induce aggressive early onset autoimmunity." (PMID 40478934, 2025). "Similarly, immune dysregulation, poly-endocrinopathy, enteropathy, X-linked (IPEX) syndrome—a rare, often fatal neonatal autoimmune disorder—is caused by mutations in the transcription factor FOXP3, which is critical for Treg development and function." (PMID 40852720, 2025). "In inflammatory settings, Treg cells upregulate Foxp3 expression and increase their suppressor function, yet both can become compromised in severe infections or autoimmunity, in particular in conjunction with genetic predispositions or interleukin (IL)-2 deprivation." (PMID 41062655, 2025). "While systemic Foxp3 degradation might have been expected to cause catastrophic autoimmunity, we find that it rather specifically augments anti-tumor T cell responses." (PMID 40478934, 2025). "Indeed, Foxp3−/− mice die at a young age from severe lymphoproliferative disease, systemic depletion of Tregs in adult mice leads to rapid lethal autoimmunity, and FOXP3 mutations in humans cause severe immune dysregulation." (PMID 38429261, 2024). "There is recent evidence that microbiota dysbiosis may be implicated in the autoimmunity induced by Foxp3+ regulatory T-cell deficiency and that microbiota remodeling significantly influences the outcome in autoimmune diseases." (PMID 38256623, 2024). "Polymorphisms in FOXP3 can impair Treg function and result in autoimmune disorders in humans." (PMID 38584670, 2024). "In addition, the rs2232365A/G FOXP3 variant is associated with prognostic outcomes and susceptibility to different autoimmune disorders, such as RA." (PMID 38584670, 2024). "Inactivating mutations in FOXP3 lead to severe autoimmunity with a scurfy phenotype in mice and Immunodysregulation Polyendocrinopathy Enteropathy X-linked (IPEX) syndrome in humans, which is manifested by immune dysregulation, polyendocrinopathy and enteropathy." (PMID 38674427, 2024). "The connection between FOXP3 and autoimmunity is well established: mutations in FOXP3 cause a systemic and severe autoimmune syndrome in humans called immunodysregulation polyendocrinopathy enteropathy X-linked (IPEX) syndrome and the equivalent scurfy in mice." (PMID 37261960, 2023). "Dysfunctional FOXP3 protein due to mutations in the FOXP3 gene results in the development of severe autoimmune disorders as can be observed in the “scurfy” mouse mutant and patients suffering from immune dysregulation, polyendocrinopathy, enteropathy, and X-linked syndrome (IPEX)." (PMID 37868998, 2023). "These variants point to genes besides FOXP3 that could influence T cell and Treg function during autoimmunity." (PMID 36032083, 2022). "In addition, we observed that the number of CD4+FoxP3+ regulatory T cells, deficiencies in which will lead to severe autoimmunity, was also reduced in the Axl-/-Mertk-/- thymus." (PMID 35967387, 2022). "The loss of FoxP3 in transferred Treg could result in the accumulation of antigen-specific effector T cells capable of aggravating autoimmunity." (PMID 36049437, 2022). "Plus, Foxp3 deficient mice (Scurfy) as well display severe autoimmunity in the gut." (PMID 35860233, 2022).
Autoimmunity (continued). "For example, deletions and mutations of FOXP3 have been found in human breast and prostate cancer samples, and germline mutations of FOXP3 result in a high rate of spontaneous breast cancer and fatal autoimmunity in mice." (PMID 34768829, 2021). "Strikingly, dysfunctional, instable or insufficient Foxp3 expression can also trigger autoimmunity: Upon loss of Foxp3, Tregs lose their immunosuppressive capacity adapting phenotype and functionality of Th cells (Th1, Th2, Th17), such as production of IFNγ and IL-17." (PMID 34691057, 2021). "The importance of Foxp3 has been illustrated by studies of Foxp3 gene mutations, immune dysregulation, polyendocrinopathy, enteropathy, and X-linked (IPEX) syndrome in humans, and Scurfy mutant mice bearing Foxp3 mutations develop lethal multi-organ autoimmunity." (PMID 33897710, 2021). "Foxp3 is the master transcription factor (TF) involved in sustaining Treg suppressive identity and mutations leading to Foxp3 loss-of-function are associated clinically with the severe autoimmunity that presents as IPEX syndrome (Immune dysregulation, Polyendocrinopathy, Enteropathy, X-linked)." (PMID 34290714, 2021). "Deficiency in Foxp3 blocks the development of natural Tregs and enhances the activity of T cells with self-antigens and thus promotes lymphoproliferative disorders and multi-organ autoimmunity." (PMID 34068092, 2021). "Likewise, Foxp3-depleted or Foxp3-mutated mice have Tregs deficiency and development of autoimmunity." (PMID 33329608, 2020). "The importance of FOXP3 in Tregs is supported by the evidence that mutations in the FOXP3 locus lead to Treg dysfunction and severe autoimmunity, as was first identified in Scurfy mutant mice and the immunodysregulation polyendocrinopathy enteropathy X-linked syndrome (IPEX) in humans." (PMID 32793236, 2020). "Mutations in the Foxp3 gene lead to fatal autoimmune disorders in both humans (IPEX—immunodysregulation, polyendocrinopathy, enteropathy, X-linked syndrome) and mice (scurfy mice), highlighting the critical role of Foxp3 for Tregs and consequently immune homeostasis." (PMID 33329406, 2020). "Because CCR8 is expressed on Foxp3+ Treg and has been implicated in their suppressive capacity in autoimmunity and cancer, it was tempting to speculate that dysregulated Treg functions contributed to exacerbated DSS colitis in Ccr8−/− mice." (PMID 33613532, 2020). "These FOXP3+ CD25high Tregs are essential for maintenance of self-tolerance because loss-of-function mutations in Foxp3 cause an early-onset, lethal autoimmune disorder known as immunodysregulation polyendocrinopathy enteropathy X-linked syndrome (IPEX) in humans and scurfy in mice." (PMID 33072087, 2020). "Insight into the Treg response to glycolysis, including transcriptional programming of splice variants of FOXP3 itself, has provided insight into loss of Treg function in autoimmunity and demonstrates that control of FOXP3 expression is important for stable suppressive function." (PMID 33072063, 2020). "However, besides these genetic alterations affecting Foxp3, loss of Treg cell function in autoimmune disorders is usually unrelated to Foxp3 mutations." (PMID 32117202, 2019). "In this study, we examine whether Baicalin treatment can effectively relieve lupus-associated autoimmunity, and the role of Baicalin on differentiation of Tfh and Foxp3+ regulatory cells in vitro and in vivo." (PMID 30760702, 2019). "Foxp3 is essential for the development, maintenance, and function of Treg cells and inactivating mutations in Foxp3 lead to the spontaneous autoimmunity with a scurfy phenotype in mice and immune dysregulation, polyendocrinopathy, enteropathy, X-linked (IPEX) syndrome in humans." (PMID 31440249, 2019). "Thus, the vigorous scurfy-like autoimmunity associated with CD25cKO mice appears to activate peripheral CD4+ Foxp3+ T cells, but these changes fail to prevent lethal disease." (PMID 30833563, 2019).
Autoimmunity (continued). "FOXP3 expression is crucial throughout the Treg cell life-time to sustain a Treg phenotype and prevent autoimmunity and defects in FOXP3 expression, which have been associated with severe autoimmune conditions." (PMID 31832140, 2019). "The most prominent example is the IPEX (immuno-dysregulation, polyendocrinopathy, enteropathy, X-linked) syndrome, a disease that develops due to mutations in the FOXP3 gene leading to Treg defects and resulting in lethal multi-organ inflammation and autoimmunity." (PMID 31920671, 2019). "Importantly, the increased Foxp3 CNS2 DNA methylation in NOD mice <30 days of age with a very early onset of autoimmunity suggests a potential causative role of miR142-3p/Tet2 signaling in promoting autoimmune activation and progression." (PMID 31836704, 2019). "Moreover, the absence or mutations of FOXP3 result in immune dysregulation and multiorgan autoimmunity." (PMID 29854846, 2018). "Because in general, patients with FoxP3 mutations exhibit excessive autoimmunity with high levels of IgE, peripheral eosinophilia and Th2 skewing, the reduced FoxP3 expression may be a contributing factor to the development of allergic diseases in humans." (PMID 30473698, 2018). "Furthermore, while mice with Treg-specific overexpression of Id2 remains disease free at an early age, steady loss of Foxp3 expression eventually results in severely diminished Treg compartment and results in systemic autoimmunity later in their life." (PMID 30413714, 2018). "Intriguingly, Lkb1-deficient Treg cells lost their linage-specific features and exhibited severe impairment in the maintenance of Foxp3 expression and suppressor function that may underlie the extremely severe autoimmunity in Foxp3CreLkb1f/f mice." (PMID 28621313, 2017). "Divers mutations in the human FOXP3 gene result in an allotropic syndrome of multi-organ autoimmunity (immune dysregulation, polyendocrinopathy, enteropathy, X-linked (IPEX) syndrome) and similar effects were observed in the scurfy mouse, a murine model carrying a mutation in Foxp3." (PMID 28098832, 2017). "Nevertheless, in this second study the frequency of CD25low FOXP3+ T cells was correlated with dsDNA antibodies levels suggesting that these cells may be directly pathogenic or biomarkers of autoimmunity in these patients." (PMID 28747257, 2017). "Interestingly, the phenotypes of autoimmunity reported in Atg7 deficient mice, align with lymphoid proliferation and increased cellularity we observe in Foxp3-Cre::Notch1lox/loxmice." (PMID 27267497, 2016). "Indeed, mice with mutations in TGF-β responsiveness, TGF-β secretion, or FoxP3 expression develop patent autoimmunity characterized by lymphoproliferation, cellular activation and pro-inflammatory cytokine secretion." (PMID 25781948, 2015). "These exFoxp3 cells which lost Foxp3 expression among Foxp3+ Treg cells develop an effector-memory phenotype, produce pathogenic cytokines, and may be involved in triggering the development of autoimmunity." (PMID 24058613, 2013). "Based on the induction of autoimmune processes caused by the FOXP3 gene mutation, it was supposed that defective Treg cells might also contribute to the development of immunopathological processes in “more common” autoimmune disorders." (PMID 23766567, 2013). "Additionally, several recent studies have demonstrated that in the inflammatory setting of autoimmunity, there is a loss of Foxp3 during inflammatory responses." (PMID 24058613, 2013). "However, FoxP3 is essential for Treg function since loss of FoxP3 function results in severe lymphoproliferative disease and autoimmunity in humans and mice." (PMID 22754651, 2012). "Furthermore, autoimmunity in Foxp3−/− mice was associated with decreased marrow LT-HSC numbers during the course of disease." (PMID 23200826, 2012). "Indeed, loss-of-function mutations of Foxp3 in mice and men, or the ablation of Foxp3+ cells in transgenic mice, all lead to lethal autoimmunity." (PMID 22783257, 2012).